EGFR (epidermal growth factor receptor)
Diseases named in the same sentence as EGFR in open-access papers (continued):
Sharing a sentence is not in itself a finding about the gene and the disease.
head and neck cancer (continued). "Furthermore, EpEX, as a ligand of EGFR, is capable of activating the EGF/EGFR signaling pathway in head and neck cancer cells." (PMID 38791091, 2024). "Thus, to explore a possible co-targeted therapy of both EGFR and MPS1 for the treatment of HNSCC, we used the UALCAN database to obtain data mainly concerning MPS1 expression and head and neck cancer." (PMID 39339232, 2024). "Similarly, EGFR activation triggers EMT, reducing cellular responsiveness to radiation and cetuximab in head and neck cancer." (PMID 39633985, 2024). "In head and neck cancer, epidermal growth factor receptor (EGFR)-mediated phosphorylation of TRIP13 (pY56) enhanced non-homologous end-joining repair and induced radiation resistance in cancer cells." (PMID 38067275, 2023). "Anti-EGFR VHH-PS monovalent conjugates resulted in tumor necrosis in approximately 90% of tumor cells, which was significantly better than the mAbs Cetuximab-PS in an orthotropic mouse tumor model of head and neck cancer." (PMID 37746282, 2023). "For examples, apigenin, which is a flavone that existed in celery and Chinese medicine Rhizoma polygoni cuspidati, was combined with epidermal growth factor receptor (EGFR) inhibitor cetuximab to synergistically down-regulate p-EGFR, p-Akt, p-STAT3 and Cyclin D1 in head and neck cancers." (PMID 37497002, 2023). "Additionally, we find that EGFR/ERK signaling pathway was disrupted by NSD3 knockdown, a finding that is consistent with current findings, as well as a study in head and neck cancer." (PMID 37062069, 2023). "Similarly to EGFR, the MET RTK is a promising candidate for targeted therapy, notably for gastric, lung, and head and neck cancer, where MET overexpression or amplification can often be observed." (PMID 37188738, 2023). "Given its immunomodulating effects and the increasingly important link between EGFR inhibitory therapies and tumor immune microenvironment, ARID1A changes may provide clues for optimizing immune checkpoint inhibitor therapy in head and neck cancers." (PMID 36362284, 2022). "Furthermore, the potential positive clinical role of Palbociclib is suggested in combination with EGFR inhibitor Cetuximab in metastatic and advanced HPV unrelated head and neck cancer." (PMID 35891353, 2022). "This phase II, Simon 2-stage, multicenter study evaluated the efficacy of the combination of CDX-3379 and cetuximab, monoclonal antibodies against ErbB3 and EGFR, respectively, in patients with recurrent/metastatic, HPV-negative, cetuximab-resistant head and neck cancer." (PMID 35625959, 2022). "Afterward, the anti-EGFR/AuNRs were incubated with head and neck cancer cells or nonmalignant epithelial cells for 30 min." (PMID 35621478, 2022). "Phase I and II clinical trials of NIR-PIT in patients with recurrent head and neck cancer (HNC), in which anti-epidermal growth factor receptor (EGFR) monoclonal antibody (mAb) conjugated to IR700 (Cetuximab-IR700) was used, showed a tolerable safety profile and promising preliminary efficacy." (PMID 35453596, 2022). "For these reasons EGFR became a popular therapeutic target; both EGFR-targeted mAbs and TKIs demonstrated efficacy in large phase III clinical trials and were approved for treating lung, colorectal and head and neck cancers." (PMID 35814399, 2022). "On the other hand, HPV+ head and neck cancers do not show concrete correlation with Notch pathway activities in angiogenesis, and are also less dependent on EGFR signalling." (PMID 34944837, 2021). "Among them, LGG, testicular germ cell carcinoma, GBM and uveal melanoma were the top four tumors with the highest average mRNA expression of LANCL2, while the average mRNA expression of EGFR was highest in GBM, head and neck cancer, clear cell renal cell carcinoma (ccRCC) and LGG." (PMID 34461927, 2021). "EGFR-targeted therapies such as cetuximab and nimotuzumab have shown improvements in progression-free survival (PFS) and overall survival (OS) in patients with head-and-neck cancers." (PMID 34104833, 2021).
head and neck cancer (continued). "In head and neck cancers, EpEX stimulation of EGFR had negative effects on EMT progression, though it promoted cell growth." (PMID 34209658, 2021). "Radiation therapy in association with cisplatin-based chemotherapy or cetuximab, a monoclonal anti-epidermal growth factor receptor (EGFR) antibody, is the cornerstone of locally advanced head and neck cancers (HNC), the concurrent treatment demonstrating a synergistic potential." (PMID 33374739, 2020). "We showed here that targeting of EGFR with a combination of antibodies against non-overlapping epitopes in head and neck cancer cells resulted in unconventional receptor uptake that was independent of canonical signalling events." (PMID 31959764, 2020). "Similarly, treatment of head and neck cancer cell lines with OSI-027, an mTORC1/2 inhibitor, synergistically enhances the effect of the reversible EGFR tyrosine kinase inhibitor erlotinib on cell survival." (PMID 31640284, 2019). "Because EGFR plays crucial roles in the biology of head and neck cancer cell lines, we verified that miR-223-3p did not inhibit the EGFR transcription/translation program." (PMID 28915663, 2017). "Targeting of EGFR and IGF-1R in a spatio-temporal manner could be a promising therapeutic strategy in head and neck cancer." (PMID 27716204, 2016). "Our results suggest that a combinatorial approach that inhibits both EGFR and IGF1R signaling may offer a worthy strategy to enhance therapeutic outcome and combat acquired resistance to cetuximab in head and neck cancer." (PMID 27716204, 2016). "Interestingly, a recent study by Nottingham and colleagues showed that IKKα and IKKβ synergistically promote the expression and activity of both EGFR and AP1 transcription factors through NF-κB-mediated transcription in head and neck cancer." (PMID 26895469, 2016). "Furthermore, the potential beneficial interaction between EGFR inhibition and radiation has been investigated as a major clinical milestone with results from phase III trial in advanced in advanced head and neck cancer patients." (PMID 26048754, 2015). "Co-inhibition of EGFR and ANO1 had an additive effect on head and neck cancer cell proliferation, suggesting that co-targeting of ANO1 and EGFR could enhance the clinical potential of EGFR-targeted therapy in HNSCC." (PMID 25823819, 2015). "In this study, the combined effects of low-intensity ultrasound (LIU) and cetuximab, an anti-epidermal growth factor receptor (EGFR) antibody, on cell killing and induction of apoptosis in HSC-3 and HSC-4 head and neck cancer cells, and its mechanisms were investigated." (PMID 23251234, 2013). "Here, we found that inhibition of EGFR by erlotinib results in phosphorylation of STAT3 at Tyr705 leading to its activation and to increased levels of Bcl2/Bcl-XL at both mRNA and protein levels in head and neck cancer cells." (PMID 24019973, 2013). "Epidermal growth factor receptor (EGFR), a member of the HER family of receptor kinases is overexpressed in a wide range of tumor types including nonsmall cell lung, pancreatic, breast and head and neck cancers with several drugs targeting this molecule." (PMID 23342262, 2012). "To our knowledge, for the first time, we have demonstrated the specific inhibition of IR-induced NFκB with irreversible EGFR TK inhibitor, EKB-569 and dissected out the functional downstream signaling that orchestrate in promoting radiosensitization at least in head neck cancer." (PMID 22242139, 2011). "Additionally, it has been described that EGFR accumulation on the cell membrane is responsible for cetuximab resistance in NSCLC and head and neck carcinoma cells." (PMID 22185378, 2011).
head and neck cancer (continued). "Thus, there seems to be an interesting crosstalk of EGFR-TGF-β and PD-1 which could be further explored in head and neck cancers and other cancer types treated with anti-EGFR or pembrolizumab alone." (PMID 40560045, 2025). "Notably, however, head and neck cancer (HNSC) has a dearth of unique CAR targets, with only two targets currently in clinical trials, EGFR and ERBB2, suggesting that there may be a critical unmet need to identify additional cell surface targets for HNSC." (PMID 37835579, 2023). "This could mean that the role of EGFR in sinonasal (non-)ITAC is not as significant as in some other head and neck carcinomas." (PMID 37370810, 2023). "Up-regulation of EGFR by squamous epithelial cells from 24 HNSCC patients with head and neck squamous cell carcinoma (HNSCC) suggests that therapies targeting these genes may be effective in the prevention of head and neck cancer." (PMID 34575510, 2021). "However, to date the EGFR inhibitor cetuximab remains to be the only molecular targeted agent approved by the U.S. Food and Drug Administration (FDA) for use with radiation therapy in head and neck cancer." (PMID 34733787, 2021). "Others demonstrated that [89Zr]Zr-cetuximab tumor uptake in patients with advanced head and neck cancer did not correlate with EGFR expression in the tumor as a continuous variable, but SUV and tumor to background ratio were significantly higher in patients with a high versus low EGFR score." (PMID 31705176, 2020). "For example, antibody-based targeting of the Epidermal Growth Factor Receptor (EGFR), Human Epidermal Growth Factor Receptor 2 (Her2), and Cluster of Differentiation 20 (CD20) are currently used as standard targeted treatments in lymphoma, breast, colorectal, and head and neck cancers." (PMID 31311081, 2019). "In addition, the cancer genome atlas (TCGA) has identified amplification and mutation of EGFR in a proportion of human papillomavirus (HPV) positive and negative head and neck cancers." (PMID 27716204, 2016). "Indeed AXL dimerization and phosphorylation of EGFR leads to the activation of phospholipase C gamma and protein kinase C that results in the activation of mTOR signaling to promote resistance to PI3K inhibition in head and neck cancer." (PMID 27834845, 2016). "Co-inhibition of EGFR and ANO1 had an additive effect on head and neck cancer cell proliferation, suggesting that co-targeting of ANO1 and EGFR could enhance the clinical potential of EGFR-targeted therapy in HNSCC and might delay or prevent resistance to single agent treatment." (PMID 25823819, 2015). "Combined inhibition of EGFR and STAT3 using erlotinib and niclosamide synergistically represses head and neck cancer in vitro and in vivo, which may represent a novel and effective therapeutic strategy for improving prognosis of patients with head and neck cancer." (PMID 24019973, 2013). "In summary, the present studies have demonstrated that inhibition of EGFR by erlotinib stimulates phosphorylation and activation of STAT3 leading to increased levels of Bcl2 and Bcl-XL, which could reduce the efficacy of erlotinib against head and neck cancer." (PMID 24019973, 2013). "In regard to the ongoing phase III study in patients with relapsed/metastatic head and neck cancers, our data provide reassurance that the eligibility criteria that allow entry of patients with platin-refractory disease, irrespective of EGFR/Ras/MAPK pathway status, are appropriate." (PMID 22920673, 2012). "Head and neck cancers are not without their fair share of responses to anti-EGFR therapies." (PMID 21274259, 2010). "Serum levels of the soluble epidermal growth factor receptor (sEGFR) and its ligands epidermal growth factor (EGF), transforming growth factor-α (TGF-α) and amphiregulin (AR) were measured in healthy donors and patients with non-small cell lung cancer (NSCLC) and head and neck carcinoma (HNC)." (PMID 17453000, 2007).
head and neck cancer (continued). "Further patient follow-up will be important in determining whether intense EGFR and TFR staining, combined with a high percentage reactivity with Ki-67 antibody and DNA aneuploidy, will ultimately define a subset of head and neck cancer patients with a poor clinical outcome." (PMID 2372483, 1990). "Here, we found that inhibition of EGFR by erlotinib stimulated phosphorylation and activation of STAT3 leading to increased Bcl2/Bcl-XL expression in head and neck cancer cells, which may dampen the therapeutic efficacy of erlotinib against head and neck cancer." (PMID 24019973, 2013). "Next, the assessment of EGFr inhibition (cetuximab), with or without the addition of JAK-STAT-3 inhibition (JAK1i), and its effect on STAT-3 protein expression in four human head and neck cancer cell lines was studied." (PMID 26458879, 2015).
head and neck squamous cell carcinoma (593 papers, 1995 to 2026). A squamous cell carcinoma that arises from any of the following anatomic sites: lip and oral cavity, nasal cavity, paranasal sinuses, pharynx, larynx, and salivary glands. "Head and neck squamous cell carcinoma (HNSCC) has an EGFR mutation frequency of 80–90%; hence, recent immunotherapeutic treatments have mainly targeted EGFR." (PMID 38675381, 2024). "Mutations in the tyrosine kinase domain of the EGFR gene on Exons 19 to 21 is one of the multiple molecular pathways of tumorigenesis in head and neck squamous cell carcinoma." (PMID 33968826, 2021). "Xiaofei examined human head and neck squamous cell carcinoma and reported that acquired resistance to erlotinib was associated with the upregulation of Mig-6 and decreased EGFR activity." (PMID 32552717, 2020). "Overexpression of the epidermal growth factor receptor (EGFR) in head and neck squamous cell carcinomas (HNSCC) is considered to cause increased EGFR activity, which adds to tumorigenicity and therapy resistance." (PMID 31537844, 2019). "In this study, we intend to determine the immunohistochemical expression of EGFR in cases of head and neck squamous cell carcinoma and its association with prognostic clinico-pathologic features." (PMID 29954411, 2018). "The overexpression or mutation of epidermal growth factor receptor (EGFR) has been associated with a number of cancers, including head and neck squamous cell carcinoma (HNSCC)." (PMID 26895469, 2016). "Epidermal growth factor receptor (EGFR) activation is a major cause of metastasis in many cancers, such as head and neck squamous cell carcinoma (HNSCC)." (PMID 25595899, 2015). "Overexpression or hyperactivation of the EGFR is associated with poor prognosis in many human cancers, including metastatic colorectal cancer (mCRC), head and neck squamous cell carcinoma (HNSCC), non-small cell lung cancer (NSCLC) and brain cancer." (PMID 25344208, 2014). "For example, EGFR overexpression is associated with poor prognosis of head and neck squamous cell carcinoma (HNSCC) leading to adoption of EGFR-targeted agents including cetuximab, a monoclonal antibody against EGFR, for clinical management." (PMID 22549044, 2012). "Epidermal growth factor receptor (EGFR) has been implicated in the pathogenesis of head and neck squamous cell carcinoma (HNSCC)." (PMID 22315058, 2012). "Although EGFR is expressed at high levels in head and neck squamous cell carcinomas (HNSCCs) and mutations are extremely rare, monotherapy with EGFR inhibitors has shown limited success." (PMID 22545054, 2012). "For example, increased epidermal growth factor receptor (EGFR) expression is associated with radioresistance in head and neck squamous cell carcinoma, suggesting that EGFR inhibition could enhance radiation therapy effectiveness." (PMID 40510341, 2025). "In addition, HER3 signaling is associated with resistance to the EGFR-targeted TKIs gefitinib in head and neck squamous cell carcinoma (HNSCC) and BC." (PMID 39020378, 2024). "Furthermore, studies have shown crosstalk between ER-mediated signals and the signaling pathway of EGFR, which has been implicated in the progression of various cancers, including head and neck squamous cell carcinoma." (PMID 37370896, 2023). "ErbB1, or Epidermal Growth Factor Receptor (EGFR), is consistently overexpressed and occasionally mutated and amplified in head and neck squamous cell carcinomas and is an established target of monoclonal antibody (mAb) therapies with a meaningful clinical impact." (PMID 36362284, 2022). "In head and neck squamous cell carcinoma (HNSCC), EGFR alterations, including overexpression and mutations, are common and associated with poor prognosis." (PMID 40364160, 2025). "Cetuximab, an EGFR inhibitor, has been associated with lower rates of anemia for locally advanced head and neck squamous cell carcinoma (HNSCC)." (PMID 35672745, 2022).